CCR2 (C-C motif chemokine receptor 2)
Diseases named in the same sentence as CCR2 in open-access papers (continued):
Sharing a sentence is not in itself a finding about the gene and the disease.
tumor (continued). "Additionally, blocking CCL7 and CCR2 with the chemokine inhibitor Bindarit and the CCR2 antagonist INCB3344, respectively, effectively reversed the recruitment of M2‐like macrophages by MYC‐overexpressing tumor cells, suggesting that the recruitment was CCL7‐CCR2 dependent." (PMID 39899538, 2025). "Similarly, the chemokine receptor CCR2 expressed by MDSCs and the chemokine CCL2 produced by tumour cells play a pivotal role in mediating the recruitment of MDSCs into tumours; in brief, iNOS in MDSCs hampers T-cell migration through its impact on the chemokine CCL2." (PMID 40429821, 2025). "Furthermore, recent research investigating MC-tumor cell interaction-related genes and microRNA expression profiles underscores the clinical relevance of CCL2 signaling and the differential expression of the CCL2/CCR2 axis in OSCC." (PMID 41445742, 2025). "By analyzing the effect of MAP2K3 expression levels on chemokines in the tumor immune microenvironment, the results showed elevated expression of several chemokines in the MAP2K3 high expression group; such as CXCL10, CCR5, CCR10, CCL5, CCL7, CCR2, and CCL22 (upper part)." (PMID 38938778, 2024). "Non-regulatory CD25+ CD45RA+ CD4+ T cells and CCR2 on granulocytes may boost the immunosuppressive characteristics of the tumor environment, thereby promoting LUAD progression." (PMID 39668823, 2024). "Furthermore, the adaptive deletion of PTEN in brain metastatic tumor cells leads to increased secretion of chemokine CCL2, which recruits microglia expressing CCL2 receptor (CCR2) to mutually promote the growth of brain metastatic tumor cells by enhancing proliferation and reducing apoptosis." (PMID 37307835, 2024). "Inducible LY6Clo CCR2-expressing NCMs could be expanded through the activation of NOD2 signaling to promote immunity against tumor metastasis independent of T and B lymphocytes." (PMID 39545417, 2024). "Given the high expression of CCR2 and migration-related genes in NOD2-dependent LY6Clo I-NCMs, we hypothesized that signaling through CCL2/CCR2 plays a role in I-NCM–induced tumor regression." (PMID 39545417, 2024). "C-C motif chemokine receptor 2 (CCR2), a C-C chemokine receptor, is mainly expressed on immune cells, like the monocytes, macrophages, and T-cells, and can recognize and bind to chemokines, such as CCL2, as well as modulate the migration of immune cells to inflammatory and tumor sites." (PMID 38874512, 2024). "The most noticeable difference was that Lesokhin’s group did not detect neutrophil accumulation in tumors upon CCR2+ cell depletion, suggesting that the sum or quantity of MDSCs may be more important than types of MDSCs in some tumor cases." (PMID 38786066, 2024). "However, CCR2 was found to be involved in MDSC egress from BM but not migration from blood to the tumor." (PMID 38786066, 2024). "Although the depletion of CCR2+ MDSCs did not lead to suppression of tumor growth or of T cells, this could be due to the aberrant excessive accumulation of neutrophils in the tumors." (PMID 38786066, 2024). "To further understand the molecular mechanism by which the FGL2-blocking scFv induces CD69+CD8+ TM cell generation, we analyzed CyTOF data for chemokine receptors (i.e., CCR2, CXCR3, CXCR2, and CX3CR1) that may affect T cell infiltration and recruitment to tumor sites." (PMID 36759517, 2023). "MDSCs have several chemokine receptors, including CCR1, CCR2, CCR3, CCR5, CCR12, CXCR2, CXCR4, and C5aR1.25In the current study, MDSCs may express CCR1, the receptor of CCL9, which mediated the migration of MDSCs to tumor tissue." (PMID 38046278, 2023). "Mice bearing SULT2B1b-tumors treated with an anti-CCR2 depleting mAb for five consecutive days were infiltrated by lower numbers of mono-DCs, identified by the expression of Ly6C, CD11b and Sca-1 markers, and failed to control tumor growth." (PMID 36792589, 2023).
tumor (continued). "Some investigators have analyzed the effect of the TME on γδ T cell recruitment in a preclinical transplantable B16 melanoma model, where human Vδ1 T cells use the CCR2/CCL2 pathway to migrate toward the tumor, where they exert critical non-redundant anti-tumor functions." (PMID 38077392, 2023). "In addition, the reduced adrenomedullin expression and proliferation of control tumor cells cultured with endothelial cells lacking Gαs were normalized in tumor cells lacking CCR2." (PMID 36374225, 2023). "To assess the diffusion of CSF1R/CCR2/TGF-β Ab from the vasculature and its ability to reach the tumor spheroids, we perfused a device with fluorescently labeled CSF1R/CCR2/TGF-β Ab and found that the drug could penetrate the spheroid compartment within 2 hours after perfusion." (PMID 38076998, 2023). "In addition to CD180, chemokine receptor type 2 (CCR2) mRNA levels were downregulated in response to AZD5153 treatment, thus BRD4 inhibition may modulate the transmigration of tumor cells within the microenvironment." (PMID 37460961, 2023). "Moreover, CCR2 and CSF1R surface proteins of MφNP may interact with CCL2 and CSF1, respectively, which are known for recruiting monocytes and macrophages into the tumor tissue." (PMID 38111068, 2023). "Strong increases toward the tumor center were observed for CXCR3+CXCR6+ cells (population 13) and CCR5+CXCR3+CXCR6+ CD8+ TRM cells (population 9), concurrent with a decrease in CCR5 single-positive (population 12) as well as CCR2+CCR5+CXCR6+ (population 3) CD8+ TRM cells." (PMID 37448786, 2023). "CCL2 increased the expression level of the CCR1 ligand CCL3 in MAMs via CCR2, and the signaling generated by the CCL3/CCR1 interaction enhanced and stabilized the cancer cell-MAM interaction in part through integrin α4 binding to VCAM1 expressed on tumor cells in an autocrine manner." (PMID 37208442, 2023). "Finally, we observed that the CCL2/CCR2-mediated trafficking of CCR2b.B7-H3.CAR-T cells to the tumor within the brain is tumor specific since we did not observe accumulation of CCR2b.B7-H3.CAR-T cells in the opposite hemisphere of the brain." (PMID 35443752, 2022). "Furthermore, tumor burden was not changed in our B16F10 metastasis model or in MC38 metastasis model in the absence of monocyte recruitment (CCR2 KO) suggesting that monocytes had little contribution to tumor growth." (PMID 35906202, 2022). "On the basis of the principle of ceRNA hypothesis, C22orf34, RFPL1S, and LINC00996 shared same expression patterns as CXCL10, CXCL9, CCL5, FCGR3A, and CCR2, all which were upregulated in tumor tissues of PTC with HT compared with those without HT." (PMID 36266640, 2022). "It should be recognized that simply targeting CCR2 or CCR5 in PDAC may still fail to sensitize a cold tumor to ICIs in the absence of a T cell–priming mechanism." (PMID 35404390, 2022). "In addition to inducing immunogenic cell death and type I IFN secretion, anthracyclines promote the recruitment of CCL2/CCR2–dependent functional antigen-presenting cells (APCs) into tumor sites but not into tumor-draining lymph nodes." (PMID 35656295, 2022). "In addition, CCR2 inhibitor treatment has been reported to enhance anti-tumor immunity in PDAC, and has shown tolerability in PDAC patients, possibly also having inhibitory effects on neural invasion or tumor innervation." (PMID 36077804, 2022). "Chemokine analysis highlighted CCR2, CXCR2, CXCR4 and C5aR ligands/chemoattractants as possible targets to decrease the immune myeloid suppressive cells in NMIBC, but also revealed a complex chemokine crosstalk, which deserve particular attention to design novel anti-tumor-treatments." (PMID 36613562, 2022). "Antibodies designed to broadly deplete TAMs, such as CCL2/CCR2 and CSF-1/CSF1-R neutralising mAbs have performed poorly in the clinic as single agents, characterised by both a lack of effect on specific pro-tumoural subsets and collateral inhibition of anti-tumour TAM activity." (PMID 35020853, 2022).
tumor (continued). "Moreover, knocking down CCR2 abrogated PCa invasiveness to the bone, whereas, in an in vivo model of PCa metastasis, inhibiting CCL2 activity with neutralizing antibodies decreased the overall tumor burden." (PMID 35406450, 2022). "Importantly, this impact on CD8+ T cell numbers appears to be restricted to the tumor, as depletion of monocytes by anti-CCR2 treatment did not impact blood CD8+ T cell frequencies following either first or second dose of OVT." (PMID 36536097, 2022). "Thus, CAFs can participate tumor progression and metastasis via CCL2/CCR2 axis." (PMID 34804061, 2021). "In WT mice housing in EE, CD8+ T cells were remarkably increased, and M2-like TAMs and G-MDSCs were decreased in the tumor microenvironment, while in CCR2−/− mice, no apparent changes of CD8+ T cells and M2-like TAMs were found between the SE and EE housing conditions." (PMID 34593796, 2021). "EPCs are recruited into ischemic or hypoxic tumours predominantly in response to chemokines (e.g., CXCL12, CCL2, CCL5) and growth factors (e.g., VEGF, bFGF), which interact with their respective receptors (e.g., CXCR4, CCR2, CCR5, VEGFR2) on the surface of EPCs." (PMID 34035882, 2021). "These inflammatory CAFs released factors that enhanced tumor cell dispersion, scattering, and migration; the inflammatory CAF-derived factors elevated cancer cell migration by stimulating the chemokine receptors CCR2, CCR5, and CXCR1/2 and Ras-activating receptors, expressed by the cancer cells." (PMID 33806906, 2021). "Thus, targeted neutralization of CCR2 or blockade of CCL2 inhibited the recruitment of TAMS and monocytic MDSC at tumor sites, angiogenesis, cancer development, and metastasis in various cancer models, among them breast cancer, lung cancer, ovarian cancer, and others." (PMID 34944943, 2021). "At the same time, there was a large overlap between the genomes of PMN-MDSCs and M-MDSCs involved in immunosuppression, such as IL-1B, ARG-2, CD84, and WFDC17, and chemokine receptors, such as CCR2 and CXCR2, revealing that MDSCs could be migrated to the primary tumor by tumor-derived chemokines." (PMID 34527668, 2021). "Interestingly, in the model, the CCR2 antagonist had no therapeutic effect on tumor cells with no CCL2 expression." (PMID 34804061, 2021). "Our findings support this hypothesis that M1 macrophage-derived EVs indeed display the tumor tropism like their donor cells dependent on chemokine signaling pathway, since a CCR2 antagonist significantly decreased the tumor accumulation of EVs." (PMID 32550891, 2020). "Since CCR2+ immune cells, particularly neutrophils, localized primarily to the VI, we hypothesized that there would be a decrease in immune cells in the VI in CCR2KO tumor animals." (PMID 32391790, 2020). "However, carlumab (CNTO 888) is well-tolerated in phase 2 trial (NCT00992186) but does not block the CCL2/CCR2 axis or show anti-tumor activity as a single agent in metastatic castration-resistant prostate cancer (CRPC)." (PMID 33224886, 2020). "Interestingly, while the size of metastasized tumor nodules was reduced by treatment with a CCR2 antagonist, the number of tumor nodules was not affected." (PMID 33260160, 2020). "Since CCR2 is crucial for many types of leukocytes to be recruited into tumor microenvironment via CCL2, the high expression of Ccr2 mRNA observed in both TRAMP-C1 and LLC derived tumor tissues may reflect the enrichment of leukocytes." (PMID 32244522, 2020). "Moreover, the CCR2 KO strain showed no significantly increased tumor proliferation following PH, and the protection observed in RIPK3 KO strain can, at least partially, be attributed to the absence of recruitment of these cells." (PMID 33178579, 2020).
tumor (continued). "Though MiV rank as the largest group in EVs, it is hard to preclude the possibility that ApB and Exo may be able to target tumor without CCR2 involvement." (PMID 32550891, 2020). "Leukocyte recruitment to the tumor site is mediated by inflammatory chemokines from the CXC subfamily (CXCL1, -2, -5, -6, and -8) as well as from the CC group (CCL2, -3, and -5), which attract leukocytes: neutrophils bearing receptors CXCR2 and CCR2-positive monocytes." (PMID 32456359, 2020). "However, through the same mechanisms of CCL2/CCR2 inhibition, ACKR2 was also reported to prevent the activities of beneficial leukocyte sub-populations, such as NK cells and neutrophils that are cytotoxic against tumor cells." (PMID 32582148, 2020). "Inhibition of CCR2 by treatment with PF-04136309 in the presence of nab-paclitaxel/gemcitabine resulted in a drop of IM in peripheral blood and tumor, but unexpectedly did not accumulate IM in the bone marrow, possibly due to compensatory activity by gemcitabine." (PMID 31297636, 2020). "Hence, we conclude that CCR2-depenednt effects observed in our studies likely reflect the production of MCP-1 by tumor cells rather than host cells." (PMID 33322474, 2020). "The first approach includes the elimination of TAM and monocyte accrual to the tumor site through the inhibition of mainly CSF-1/CSF-1R (Colony Stimulating Factor 1/ Colony Stimulating Factor 1 Receptor) and CCL2/CCR2 (C-C Motif Chemokine Ligand 2/ C-C Motif Chemokine Receptor 2) signaling axes." (PMID 31060337, 2019). "Therefore, the reduction in intermediate monocytes present in GBM patients, coupled with the simultaneous increase in CCR2 expression in this cell subset, suggests the possibility that CD14+/CD16+ monocytes represent the cell subset actively recruited to the tumor in GBM patients." (PMID 30813960, 2019). "Nevertheless, the use of either CCL2 or CCR2 inhibitors, in clinical trials, gave disappointing results, indicating the need of supplementary studies considering the presence of potential TME-dependent compensatory mechanisms acting on tumor-resident myeloid cells." (PMID 31447834, 2019). "Interestingly, some investigations using CSF-1R or CCR2 inhibitors showed that the anti-tumor efficacy of these drugs was to reprogram TAMs, rather than macrophage depletion, as supposed previously." (PMID 31878087, 2019). "In this regard, a pre-clinical study demonstrated that a CCR2 antagonist shows anti-cancer effects increasing CD8+ T cells via blocking tumor-infiltrating macrophage-mediated immunosuppression, and that the anti-tumor effect was improved by combining the antagonist with low-dose sorafenib." (PMID 31377844, 2019). "TAMs express chemokine (C-C motif) receptor type 2 (CCR2), a chemokine receptor that interacts with chemokine (C-C motif) ligand 2 (CCL2) and exerts a pro-tumoral role mediating tumor proliferation, angiogenesis, and chemotaxis of immune suppressive cells to the tumor stroma." (PMID 29301364, 2018). "However, genetic deletion of CCR2 (myeloid cell) had no impact on primary tumor formation on the KPC model." (PMID 29719257, 2018). "Importantly, the difference in tumor burden between pLKO.1 and shTRAIL-R tumors was completely absent when the host was devoid of CCR2." (PMID 28212753, 2017). "In contrast, downregulation of CC inflammatory chemokine receptors, namely CCR5, CCR2, and CCR1, was a common feature of primary Mn and Mn-derived Mf response to low pO2 and an important mechanism regulating their retainment/concentration in hypoxic areas of inflammatory and tumor lesions." (PMID 28936211, 2017). "Our results demonstrated that CCR2+Ly6Chi monocytic myeloid cells regulate tumor response to radiation by suppressing T cell function instead of impacting vascularization in tumors, thereby eliminating the MDSC population enhanced T cell function as well as the anti-tumor response to radiation." (PMID 29170400, 2017).
tumor (continued). "Although the Colon38 tumor model has a minimal regulatory T cell (Treg) component, CCR2/CCR5 antagonism in tumors with abundant Tregs could offer additional benefits by targeting Tregs as well as IM post-RT and promote anti-tumor immunity by blocking two modes of immunosuppression." (PMID 27852031, 2016). "We found that the number of circulating EPCs increased in tumor-bearing mice compared to tumor-free mice and that disruption of Ccl2 and Ccr2 had profound effects on circulating EPC numbers: EPCs were greatly reduced in Ccl2-/- mice and increased in Ccr2-/- mice." (PMID 27820834, 2016). "CCR2+ T cells were nearly absent in FoxP3+CD4+ T cell fractions, indicating that HNSCC-circulating aTreg cells may be recruited to the tumor microenvironment by endogenous MCP-1 via binding to CCR4 but not CCR2." (PMID 27177223, 2016). "Interestingly, the number of metastatic tumor nodules in the lung of CCR2−/− mice was not significantly different from that of MCP-1−/− mice (data not shown)." (PMID 23527025, 2013). "If so, why is the absence of CCR2+ cells so critical for tumor support?" (PMID 22279523, 2012). "Here we show that in the absence of CCR2, F4/80+ cells also do not accumulate at the tumor site." (PMID 22279523, 2012). "Finally, intrathymic negative selection similarly ensued in CCR2-competent mice once the tumor-specific antigen was secreted into bloodstream." (PMID 22815949, 2012). "In an attempt to study the distinguishable contribution of non-malignant CCR2+ cells at the tumor site to tumor development and angiogenesis, wild-type and CCR2−/− C57BL/6 mice were administrated with 7×106 CCR2+ TRAMP C1.luc cells that stably over-express a luciferase reporter gene." (PMID 22279523, 2012). "After all, BM CCR2 monocytic cells, neutrophils, and myeloid-derived suppressor cells also contribute to tumor development and progression by producing VEGF and other angiogenic factors, and they are the vast majority of CD11b+ cells that home to the tumor site." (PMID 22279523, 2012). "To address this question we have generated an adoptive transfer system in which purified BM GFP+ cells from CCR2+ mice harboring a targeted replacement of the CX3CR1gene by EGFP reporter gene (cx3cr1gfp), together with the CD45.1 congene, were transplanted into CCR2−/− mice bearing a CCR2+ tumor." (PMID 22279523, 2012). "Whereas previous studies have shown that targeting suppressive monocytes in PDAC with a CCR2 inhibitor could enhance chemotherapy, in our current study, inhibition of monocytes from entering the tumor with a CCR2 inhibitor did not significantly affect the chemo/anti-LIF/anti-PD-L1 response." (PMID 39857986, 2025). "Notably, chemokine receptors, including C-C chemokine receptor type 2, 4, 5, 6, 8, 10 (CCR2, CCR4, CCR5, CCR6, CCR8, CCR10), and C-X-C chemokine receptor type 3, 4 (CXCR3, CXCR4) have been identified as significant factors in the recruitment of Treg cells to the tumor site." (PMID 39000453, 2024). "In addition to enhancing tumor-specific cytotoxic T cell responses, future immunotherapeutic approaches may need to focus on the immunosuppressive TME, including the role of CCR2+ monocytes, and the interplay with IFN-γ and IL-6 in HNSCC and the patients’ blood." (PMID 39882242, 2024). "The genetic deletion of CcR2 produced a notable absence of macrophages in the tumour environment without seeing any remarkable differences between overall survival differences, nor a particular synergistic effect with a pre-existing absence of TAMs paired with tumour irradiation." (PMID 37232837, 2023). "To determine whether turnover of resident macrophages occurs through replacement by blood monocytes, we evaluated F4/80- and CCR2-expressing macrophages, but these cells were not altered by clodronate liposomes treatment, so the macrophages in the local tumor site were similar to TRMs." (PMID 35326625, 2022).